TIMP2 (TIMP metallopeptidase inhibitor 2)
Diseases named in the same sentence as TIMP2 in open-access papers (continued):
Sharing a sentence is not in itself a finding about the gene and the disease.
Stroke (8 papers, 2014 to 2025). Sudden impairment of blood flow to a part of the brain due to occlusion or rupture of an artery to the brain. "TIMP-2 showed neuroprotective effects in an animal model of stroke by reducing the proteolytic opening of the blood-brain barrier and subsequent intracerebral hemorrhage." (PMID 24970341, 2014). "TIMP-2 was significantly increased in the serum or cerebrospinal fluid (CSF) of stroke, MS, AD, or HD patients, suggesting the protective role of TIMP-2 in neurological disorders." (PMID 24970341, 2014). "However, we cannot exclude that the increasing expression of Timp-2, Timp-3 and Timp-4 mRNA also facilitates brain repair after a stroke by increasing cell proliferation and/or differentiation." (PMID 30062663, 2019). "Previous work suggests that TIMP2 activity was maximally increased only at 5 days after tMCAO, indicating that TIMP2 might have a role at a later time after the stroke onset." (PMID 29452577, 2018). "Therefore, TIMP-2 has been suggested to be a therapeutic candidate for CNS disorders, such as MS, stroke, and Parkinson’s disease." (PMID 24970341, 2014). "In a study examining human brain samples after a fatal stroke, MMP-9 and TIMP-2 demonstrated higher expression in brain microvessels, prompting the hypothesis of selectively targeting these molecules for “vasculoprotection” following stroke." (PMID 26074872, 2015). "Data from an in vitro stroke model of a human brain microvascular endothelial cell line show favorable effect of statin pretreatment on the MMPs metabolism, mainly by induced the expression and secretion of TIMP-1 and TIMP-2." (PMID 29435135, 2018).
acne (7 papers, 2019 to 2024). An inflammatory process of the sebaceous glands which is characterized by comedones, nodules, papules and/or pustules on the skin. "A recently published genetic study suggests that the MMP2 (−1306 C/T) polymorphism, in combination with the TIMP2 (−418 G/C) polymorphism, is associated with an increased risk of acne." (PMID 34133464, 2021). "TIMP-2 gene mutations have been associated with many diseases, including acne vulgaris, intracerebral hemorrhage, and cancer." (PMID 33027062, 2020). "In summary, this study suggests that the MMP-2 (-1306C/T) polymorphism in combination with the TIMP-2 (-418G/C) polymorphism are associated with an increased risk of acne in the Chinese Han population." (PMID 31032338, 2019). "Our study is consistent with the results of TIMP-2 (-418G/C) in this report, but we found that patients with the MMP-2 (-1306C/T) polymorphism and with the MMP-2 CT/TIMP-2 GG or GC allele are at higher risk of acne vulgaris." (PMID 31032338, 2019). "The aim of this study was to investigate the association of MMP-2 (-1306C/T) and TIMP-2 (-418G/C) polymorphisms with the risk of acne vulgaris in a Chinese Han population." (PMID 31032338, 2019). "This study indicated that the MMP-2 (-1306C/T) polymorphism, in combination with the TIMP-2 (-418G/C) polymorphism, contributes to acne vulgaris susceptibility in the Chinese Han population." (PMID 31032338, 2019). "Further research has found that the TIMP‐2 (−418 G/C) polymorphism is distributed differently in acne patients compared with controls, suggesting that the TIMP‐2 genotype may disrupt the balance between MMPs and TIMPs, increasing the tendency to develop acne." (PMID 39297226, 2024). "A study on the risk of acne scarring in the Chinese Han population related to the TIMP2 gene mutation rs4789932 suggests that changes in the expression of this gene may disrupt the TIMP/MMP balance, leading to the formation of acne scars." (PMID 39297226, 2024). "The aims of this study were to investigate the association of MMP-2 (-1306C/T) and TIMP-2 (-418G/C) polymorphisms with the risk of acne vulgaris in a Chinese Han population and to explore the correlation of clinical phenotype and family history in acne vulgaris patients." (PMID 31032338, 2019). "However, few studies have reported correlations of MMP-2 and TIMP-2 polymorphisms with acne." (PMID 31032338, 2019). "Moreover, patients with the MMP-2 CT/TIMP-2 GG genotype were at higher risk of acne, suggesting that MMP-2 gene activity might be downregulated in acne vulgaris." (PMID 31032338, 2019). "We identified IL8 and TIMP2 as key factors for wound healing by analyzing the cytokine profile of C. acnes treated HaCaT cells in vitro and cotton swab samples of acne pimple scars site in vivo." (PMID 39194729, 2024). "The effects of MMP-2 (-1306C/T) and TIMP-2 (-418 G/C) polymorphisms on MMP-2 gene activity and the risk of acne vulgaris deserve further investigation." (PMID 31032338, 2019). "A similar model of the association of TIMP-2 with scar formation was shown by comparing preparations of normal skin without inflammatory lesions in acne patients with a tendency toward scarring and without a tendency toward scar formation." (PMID 38398480, 2024). "In this study, a higher percentage of subjects had the MMP-2 CT/TIMP-2 GC genotype in the acne group than in the control group, suggesting that other polymorphisms might interact collectively in MMP-2 and TIMP-2 activity in acne vulgaris." (PMID 31032338, 2019). "Therefore, a better understanding of the correlation between phenotypes and genotypes of MMP-2 and TIMP-2 in patients with acne may help to further elucidate disease mechanisms." (PMID 31032338, 2019). "We performed acne scar cytokine profiling and found that Interleukin 8 (IL8) and Tissue inhibitor of metalloproteinases 2 (TIMP2) were significant factors at the wounded site." (PMID 39194729, 2024).
acne (continued). "Although the focus of the research is on TIMP2, it highlights the importance of the TIMP family in the pathogenesis of acne." (PMID 39297226, 2024). "Significantly increased expression of TLR-4, IL-2, IL-10, and TIMP-2 and decreased MMP-9 havebeen demonstrated in patients with acne prone to scarring." (PMID 38398480, 2024). "Our study suggests that MMP-2 CT/TIMP-2 GG genotype may correspond to decreased activity of MMP-2, which may lead to the high expression of IL-1a and β, TNF-α, and triglycerides observed in acne patients." (PMID 31032338, 2019).
asthma (7 papers, 2014 to 2025). "Low sputum MMP-9/TIMP2 ratios are associated with airway narrowing in smokers with asthma and MMP-9/TIMP-1 ratios correlate inversely with airway wall thickness assessed by CT scanning in asthmatics." (PMID 33718297, 2021). "TIMP-2 suppressed the infiltration of eosinophils and lymphocytes and suppressed airway inflammation in a mouse model of asthma." (PMID 40565065, 2025). "Since TIMP2 enhances the expression of c-fos activation, this suggests a possible link to asthma as c-fos protein, and neuropeptide content in the lungs of asthmatic rats is related to asthma attacks." (PMID 36624735, 2022). "Significant increases in tracheal wash TIMP-2 concentration between different severity grades of equine asthma were found rising from 99.3 ± 13.8 ng/ml in mildly to 169.5 ± 6.8 ng/ml in severely affected horses." (PMID 31316303, 2019). "This includes asthma, where reduced airway inflammation and hyperresponsiveness was reported after local bronchial application of synthetic TIMP-2." (PMID 27938355, 2016). "In men, increases in TIMP-1 and TIMP-2 have been found in asthma and COPD." (PMID 26770019, 2015). "TIMP-1 and TIMP-2 concentrations as well as MMP-TIMP ratios have also been studied in equine asthma showing increased levels of TIMPs in mild-to-moderate as well as severe equine asthma compared to controls and normalization of MMP-TIMP ratios under budesonide therapy." (PMID 31316303, 2019).
bladder cancer (7 papers, 2012 to 2023). "In bladder cancer, levels of MMP-2 and MMP-9 have been shown to be diminished by curcumin with an increase of tissue inhibitor of metalloproteinase-2 (TIMP-2) as the relevant underlying mechanism." (PMID 32466578, 2020). "In the case of TIMP-2, two studies analyzing serum and plasma levels reported higher serum and plasma concentrations in controls than in bladder cancer patients." (PMID 22852097, 2012). "Here, we reported that hAM preparations (homogenate and extract) inhibited the expression of the epithelial–mesenchymal transition markers N-cadherin and MMP-2 in bladder cancer urothelial cells in a dose-dependent manner, while increasing the secretion of TIMP-2." (PMID 37932474, 2023). "As an example, the TIMP2 and ITIH5 genes showed decreased 5hmC in gene bodies in bladder cancer compared with the normal bladder samples, and hMeDip-qPCR/MeDip-qPCR verified the increase in 5hmC and a relative decrease in 5mC." (PMID 30005692, 2018).
Cirrhosis (7 papers, 2011 to 2023). A chronic disorder of the liver in which liver tissue becomes scarred and is partially replaced by regenerative nodules and fibrotic tissue resulting in loss of liver function. "TIMP-1 and TIMP-2 expression were significantly increased in a small number of PBC cirrhosis." (PMID 36551935, 2022). "Therefore, we sought to determine expression of the rat genes Mmp2, Mmp9, Timp1 and Timp2 in the liver of CCl4-treated rats with different degrees of cirrhosis." (PMID 21813019, 2011). "After 20 weeks of treatment with CCl4, the hamsters of the cirrhosis group displayed alterations in the expression of genes responsible for regulating the degradation of the extracellular matrix, such as MMP-13 and TIMP-2." (PMID 30643808, 2018). "On the other hand, compared to the cirrhosis and placebo groups, the animals treated with doxazosin and carvedilol showed a 2-fold greater expression of MMP-13 and a lower expression of TIMP-2 (p<0.05), both of which reached levels similar to the intact group." (PMID 30643808, 2018). "Compared to the intact group, the group with cirrhosis exhibited a decrease in the level of MMP-13 and a 3-fold increase in the level of TIMP-2." (PMID 30643808, 2018). "In the cirrhosis group, the level of MMP-13 decreased and that of TIMP-2 increased, thus inhibiting MMP activity." (PMID 30643808, 2018). "The expression of TIMP-2 decreased and that of MMP-13 increases in animals treated with adrenoblockers with respect to the group with cirrhosis." (PMID 30643808, 2018). "In established end-stage injury with cirrhosis there is increased expression of MMP-2, MMP-9, MMP-14 as well as TIMP-1 and TIMP-2." (PMID 25076423, 2014).
diabetic nephropathy (7 papers, 2020 to 2025). "Another study showed that Mettl3 promotes podocyte injury in diabetic nephropathy via TIMP2 mRNA m6A modification." (PMID 40765834, 2025). "In this group, we showed a significant increase in the concentration of MMP-2 and TIMP-2 in diabetic nephropathy, which is consistent with the results of previous studies." (PMID 38610612, 2024). "The M6A modification of TIMP2 mRNA mediated by METTL3 in podocyte injury in diabetic nephropathy not only promotes inflammatory damage, but also apoptosis." (PMID 37865763, 2023). "Moreover, the presence of diabetic nephropathy had a significant impact on the MMP-2/TIMP-2 system." (PMID 38610612, 2024). "In the development of diabetic nephropathy, with the assistance of IGF2BP2, METTL3-mediated M6A modification of TIMP2 is involved in inflammatory damage in podocytes by regulating Notch signaling." (PMID 37865763, 2023). "Diabetic nephropathy (DN) patients had a significant reduction in serum levels of MMP2, TIMP1 and TIMP2 compared to the controls." (PMID 37445827, 2023). "TIMP-2 concentrations were also significantly higher in patients with diabetic nephropathy [131 (121.0–178.5) ng/mL] compared to those not suffering from the disease [89.8 (74.0–112.5) ng/mL, p = 0.007]." (PMID 38610612, 2024). "In some studies, circulating concentrations of TIMP-1 and TIMP-2 are decreased in patients with type 2 diabetes and diabetic nephropathy when compared to non-diabetic CKD or patients with diabetes alone." (PMID 32046355, 2020). "An imbalance between MMP2 and TIMP2 contributes to ECM accumulation and fibrosis in diabetic nephropathy, an effect that may be mediated at least in part by TGF-β, which was also dysregulated in the present study." (PMID 32787975, 2020).
fibrosis (7 papers, 2015 to 2025). the formation of excess fibrous connective tissue in an organ or tissue in a reparative or reactive process. "This study highlights the association of α-smooth muscle actin (α-SMA), a marker of activation of hepatic stellate cells, pro-MMP2, TIMP1 and TIMP2 with severity of fibrosis in NAFLD patients, whereas pro-MMP9 is rather associated with the severity of inflammation." (PMID 37445827, 2023). "As a result of this, ISO-injured mice presented with a significant reduction in LV MMP-13/TIMP-1 (by ~ 60%), MMP-9/TIMP-1 (by ~ 55%) and MMP-2/TIMP-2 (by ~ 65%) ratios at day 14 post-injury, in line with the increased LV fibrosis in these mice." (PMID 41382190, 2025). "The interstitial collagenases MMP-2 and MMP-13 are upregulated during resolution of fibrosis, while TIMP-1 and TIMP-2 inhibit MMP activity." (PMID 26374068, 2015).
ischemia (7 papers, 2020 to 2025). A hypoperfusion of the BLOOD through an organ or tissue caused by a PATHOLOGIC CONSTRICTION or obstruction of its BLOOD VESSELS, or an absence of BLOOD CIRCULATION. "Exosomes derived from TIMP2-modified ucMSCs repaired the ischemia injuries by inhibiting apoptosis and promoting angiogenesis, and ECM remodeling in cardiomyocytes." (PMID 36839879, 2023). "Moreover, ischemia injury was repaired by the treatment of cardiomyocytes with EVs loaded with TIMP2 protein." (PMID 36839879, 2023). "After ischemia, upregulated expression of tissue inhibitors TIMP1, TIMP2, TIMP3 and CTGF was observed in both the necrotic and salvaged myocardium." (PMID 32727469, 2020). "Molecular analysis revealed an increase in TIMP1, TIMP2, and TIMP3 mRNA expression soon after ischemia onset in the whole area at risk, while no variations in the evaluated MMPs were observed." (PMID 32727469, 2020).
ovarian tumors (7 papers, 1999 to 2022). "(ii) The levels of TIMP-2 and -3 increased with WHO classification of ovarian tumors particularly, with Type 2 ovarian tumors, showing greater intensity of staining of TIMP-2 than -3 relative to control." (PMID 35047406, 2021). "Significant differences in the expression of TIMP-2 were observed between normal/benign and Type 2 ovarian tumors." (PMID 35047406, 2021). "Expression of TIMP-2 was significantly enhanced in high-grade ovarian tumours compared to benign tumours." (PMID 33023532, 2020). "Previous reports on the expression of TIMP-2 in ovarian tumours and its prognostic impact on the clinical outcome in patients have been ambiguous." (PMID 33023532, 2020). "Collagen I, also present in the ovarian tumours, then induces these fibroblasts to activate proMMP-2 even in the presence of TIMP-2." (PMID 10408832, 1999). "However, we show low expression of TIMP-1 in ovarian tumors compared to the expression of TIMP-2 and -3." (PMID 35047406, 2021). "Whether this persistent STAT3 activation is responsible for enhanced expression of TIMP-2 in ovarian tumours or enhanced expression of TIMP-2 drives constitutive STAT3 activation remains to be determined." (PMID 33023532, 2020). "These indefinite findings regarding the expression of TIMP-2 in ovarian tumours may be due to different affinities of the antibodies used and differences in the experimental methods used for analysis of the studied protein." (PMID 33023532, 2020). "We propose that the growth and invasive functions of TIMP-2 in ovarian tumour biology in vitro is MMP-dependent and are regulated by MT1-MMP, while the chemosensitivity aspect may be dependent on chemotherapy-induced activation of the STAT3 pathway." (PMID 33023532, 2020). "By univariate analysis, high levels of MMP-2, MMP-9, MT1-MMP and TIMP-2, were detected by immunohistochemistry and/or mRNA in situ hybridization in tumor cells from peritoneal or pleural effusions, metastatic lesions and primary ovarian tumors." (PMID 22200690, 2012). "We propose that, in the ovarian tumour microenvironment, interaction between tumour cells and fibroblasts may enhance fibroblast production of the proMMP-2 and TIMP-2." (PMID 10408832, 1999). "Contrary to the immunohistochemistry expression of TIMP-1 in ovarian tumors, the concentration of TIMP-1, measured by ELISA, was much higher than the concentrations of TIMP-2 and TIMP-3 (***p>0.0001 vs TIMP-3; *p>0.05 vs TIMP-2) in the ascites of CN patients." (PMID 35047406, 2021). "There was no apparent difference in the expression of GLUT1 between the groups of tumours, indicating that the knock down of TIMP-2 in ovarian tumours may not be connected to GLUT1 mediated pathways." (PMID 36585738, 2022). "However, as both TIMP-2 and STAT3 are overexpressed in ovarian tumours, activated STAT3 and high TIMP-2 expression may play a dual role in maintaining in vivo ovarian tumourigenesis." (PMID 33023532, 2020).
preeclampsia (7 papers, 2009 to 2022). Preeclampsia is a hypertensive disorder of pregnancy that is characterized by new-onset hypertension with proteinuria presenting after 20 weeks of gestation, and depending on mild or severe forms may initially present with severe headache, visual disturbances, and hyperreflexia. "This study aimed to assess the potential role of MMP1, MMP9, TIMP1 and TIMP2 gene polymorphisms in the pathogenesis of preeclampsia." (PMID 35885543, 2022). "Dysregulation interplay between MMP-2, -9, and their natural tissue inhibitors TIMP-2 and -1 might be one of the possible causes for pathological collagen types I and IV turnover in preeclampsia." (PMID 33803206, 2021). "The results indicated low levels of expression of TIMP-1 and TIMP-2 in the gestational hypertension group." (PMID 33803206, 2021). "The authors concluded that higher amniotic fluid MMP-2 and TIMP-2 levels are found in women who eventually develop preeclampsia." (PMID 33803206, 2021). "The authors reported weak positive correlations between maternal age and TIMP-1 in the gestational hypertension group and between gestational age and TIMP-2 in the control group." (PMID 33803206, 2021). "sTNF-R1, Axl, and TIMP-2 were found elevated in patients with preeclampsia compared to gestational hypertensive patients and health pregnant controls." (PMID 34012435, 2021). "Higher amniotic fluid MMP-2 and TIMP-2 levels are found in women who eventually develop preeclampsia." (PMID 19698156, 2009). "In conclusion, higher levels of MMP-2 and TIMP-2 are found in the amniotic fluid of women prior to presentation of preeclampsia." (PMID 19698156, 2009). "In addition, the plasma MMP-2 levels and MMP-2/TIMP-2 ratios in pregnant women with gestational hypertension were significantly elevated as compared with healthy pregnancies." (PMID 33803206, 2021). "The decrease in MMP-2 and MMP-9 activity or ratios of MMP-2/TIMP-2 and MMP-9/TIMP-1 might be involved in the pathogeneses of early pregnancy loss and preeclampsia." (PMID 33796532, 2021). "Palei 2012, found that pregnant women with preeclampsia had significantly higher plasma MMP-2 and TIMP-2 concentrations than healthy pregnant, although the MMP-2/TIMP-2 ratios were similar." (PMID 33803206, 2021). "The TIMP-2 levels in nonpregnant women were lower than those found in normotensive pregnant controls, gestational hypertension, and preeclampsia." (PMID 33803206, 2021). "Plasma TIMP-2 in non-pregnant subjects was higher than normotensive pregnant subjects, but significantly lower than gestational hypertension patients." (PMID 33803206, 2021).